RET (ret proto-oncogene)
Diseases named in the same sentence as RET in open-access papers (continued):
Sharing a sentence is not in itself a finding about the gene and the disease.
hyperparathyroidism (56 papers, 2011 to 2025). Hyperfunction of the parathyroid glands resulting in the overproduction of parathyroid hormone. "Besides, we also found RET G691S/S904S polymorphism in this patient, but additional studies are required to explore the role of the RET gene in medullary sponge kidney with hyperparathyroidism." (PMID 29983117, 2018). "Several genes have been established as containing disease-causing mutations for the familial PHPT: MEN1 gene for MEN1, RET gene for MEN2A, CASR gene for neonatal severe hyperparathyroidism, and CDC73 gene for HPT-JT." (PMID 35586626, 2022). "Genes associated with hyperparathyroidism include MEN1, MEN2A, CDC73, CCND1, RET, CASR, and CDKN1B." (PMID 40149408, 2025). "While MEN1, MEN4, and hyperparathyroidism-jaw tumor syndrome involve inactivating pathogenic variants of tumor suppressor genes MEN1, CDKN1B, and CDC73, respectively, MEN2 is caused by activating mutations of RET proto-oncogene." (PMID 40277809, 2025). "It has been speculated that variation of the RET gene may lead to hyperparathyroidism in MSK patients." (PMID 36408280, 2022). "To date, reports have shown that more than 10% of patients with hyperparathyroidism may have a germline mutation involving the MEN1, RET, cell division cycle 73 (CDC73), calcium-sensing receptor (CASR), cyclin-dependent kinase inhibitor (CDNK1B), or PTH genes." (PMID 29983117, 2018). "Given the key role of the GDNF and RET interaction in kidney and urinary tract development, we also analyzed and found RET G691S/S904S polymorphism in this patient, but additional studies are required to explore the exact mechanism of the RET gene in MSK with hyperparathyroidism." (PMID 29983117, 2018). "Among the many PPGL susceptibility genes, RET is a well-known protooncogene, germline mutations of which cause multiple endocrine neoplasia type 2 (MEN2), which is characterized by medullary thyroid carcinoma (MTC), PCC, and hyperparathyroidism." (PMID 29850289, 2018). "However, the exact mechanism of RET G691S/S904S polymorphism in the pathogenesis of MSK and hyperparathyroidism still remains to be uncovered." (PMID 29983117, 2018). "Besides, we also found RET G691S/S904S polymorphism in this patient, but additional studies are required to explore the exact mechanism of the RET gene in MSK with hyperparathyroidism." (PMID 29983117, 2018). "Because part of the differential diagnosisincluded parathyroid carcinoma and hyperparathyroidism–jaw tumor syndrome,genetic testing for MEN1, CDC73,AP2S1, CASR, CDKN1B,GNA11 and RET was ordered and resultednegative." (PMID 39700332, 2024). "Several responsible genetic germline changes associated with parathyroid tumors in familial syndromes, such as MEN1 in MEN 1, RET in MEN 2 A, and CDC73/HRPT2 in HPT-JS (hyperparathyroidism-jaw tumor syndrome), have been identified." (PMID 30104706, 2018).
neuroblastoma (46 papers, 2005 to 2025). Neuroblastoma (NB) is the most common solid, extracranial childhood tumor. "High expression of RET has been already associated with poorer prognosis in other cancer entities such as neuroblastoma." (PMID 39825568, 2025). "Further, in vitro deletion of these three enhancers in the human neuroblastoma SK-N-SH cell line leads to loss of RET expression, providing evidence of their direct role in RET regulation." (PMID 37948459, 2023). "RET expression is also associated with increased neuroblastoma metastases in vivo, and RET expression is higher in neuroblastoma tumors from patients with stage 4 and high-risk disease." (PMID 31695841, 2019). "We have previously demonstrated synergistic efficacy of the combinations of RET inhibitors with 13-cis-retinoic acid, a vitamin A analog currently used as maintenance therapy in children with high-risk neuroblastoma." (PMID 31695841, 2019). "A recently described subset of approximately 10% of primary neuroblastoma tumors with ALK mutations has been shown to be driven through RET upregulation." (PMID 31695841, 2019). "Altogether, our findings demonstrate the critical role of activated ALK in SNS development and pathogenesis and identify RET as a therapeutic target in ALK mutated neuroblastoma." (PMID 24811913, 2014). "So, the possibility that RET gene is associated with neuroblastoma carcinogenesis has been investigated by several research groups." (PMID 22429913, 2012). "recently showed that loss of RET promotes mesenchymal identity in neuroblastoma cells." (PMID 34716856, 2022). "RET has been implicated in neuroblastoma and shown to promote cell proliferation." (PMID 31819055, 2019). "Finally, the role of RET in neuroblastoma seems to be strongly associated with the induction of neuroblastoma cell maturation by retinoic acid." (PMID 22429913, 2012). "Recently it has been more precisely defined that RET hyperactivation is driven by ALK in neuroblastoma." (PMID 38666930, 2024). "We therefore generated a CRISPR-Cas9 TMEM127-knockout (KO) and control (Mock-KO) in human neuroblastoma cell line SH-SY5Y, which endogenously expresses RET and TMEM127, to explore the effects of TMEM127 loss of function on RET localization and functions." (PMID 38687678, 2024). "RET signaling crosstalk has been reported in cell line models of other CNS tumors, including neuroblastoma." (PMID 36918928, 2023). "RET is highly expressed in multiple neuroblastoma cell lines, along with TRK family receptors (TrkA and TrkB)." (PMID 36918928, 2023). "We show that their knockdown in human neuroblastoma SK-N-SH cells reduces RET and/or EDNRB gene expression, expanding the RET-EDNRB GRN." (PMID 37948459, 2023). "The receptor tyrosine kinase RET is known to be expressed in most neuroblastoma cell lines and is required for neurodevelopment." (PMID 38155222, 2023). "Pioneer studies reporting RET expression and function in neuroblastoma models date back to more than 30 years ago, but the actual implications of this kinase in neuroblastoma pathogenesis have recently started emerge." (PMID 34716856, 2022). "Knockdown of RET was first established in mouse N2A neuroblastoma cells using a panel of shRNAs, from which we selected the two most effective to prepare lentiviral vectors in Lenti-HEK293 cells." (PMID 35798698, 2022). "VGF is known to be induced by neurotrophic factors (e.g. BDNF and NGF) and also shows up-regulation after RET activation in neuroblastoma cells." (PMID 35012575, 2022). "We additionally analyzed RET expression across 1378 cancer cell lines from the Cancer Cell Line Encyclopedia (depmap portal) and found that neuroblastoma cell lines display the highest mean RET mRNA expression." (PMID 34716856, 2022). "Several groups have started to focus on targeting RET signaling as a novel strategy against neuroblastoma tumors, showing promising results that demand further efforts and clarification." (PMID 34716856, 2022).
neuroblastoma (continued). "The literature investigating GDNF-RET signalling predominantly originates from experiments in cancer cell lines, such as SH-SY5Y neuroblastoma lines, which express RET at high levels following retinoic acid differentiation." (PMID 35798698, 2022). "Chen and colleagues illustrated that regorafenib potently inhibits RET activity and RET-mediated PI3K/AKT signaling in neuroblastoma cells to inhibit their growth in vitro and in vivo." (PMID 35957881, 2022). "In summary, a growing body of literature suggests that RET plays an important role promoting neuroblastoma tumorigenesis and aggressive phenotypes." (PMID 34716856, 2022). "Despite the findings above, other groups have presented data pointing to a role for RET in neuroblastoma differentiation in the context of retinoic acid (RA)-induced differentiation." (PMID 34716856, 2022). "Here, we investigated ALK and RET in neuroblastoma, with the aim of better understanding their respective contributions." (PMID 33921066, 2021). "The anaplastic lymphoma kinase (ALK) and rearranged during transfection (RET) receptor tyrosine kinases (RTKs) are expressed in both the developing neural crest and the pediatric cancer neuroblastoma." (PMID 33921066, 2021). "Using CRISPR/Cas9, we generated RET knockout neuroblastoma cell lines and performed a multi-omics approach, combining RNA-Seq and proteomics to characterize the effect of deleting RET in a neuroblastoma context." (PMID 33921066, 2021). "RXDX-105 treatment of neuroblastoma cells and xenograft tumors results in inhibition of RET and the RAS-MAPK pathway, adding further evidence to the critical roles these proteins and pathways play in neuroblastoma tumorigenesis." (PMID 31695841, 2019). "Our results add further evidence that RET plays a significant role in neuroblastoma cell proliferation and survival and that the RET kinase represents a promising therapeutic target." (PMID 31695841, 2019). "Prior studies of RET inhibitors have also demonstrated efficacy against neuroblastoma in vitro and in vivo through decreasing neuroblastoma viability and induction of apoptosis." (PMID 31695841, 2019). "RET has been previously shown to be highly expressed in neuroblastoma cells, and constitutively activated RET enhances neuroblastoma metastases in vivo." (PMID 31695841, 2019). "RET has also been shown to be expressed on neuroblastoma tumor cells, and transgenic mice overexpressing RET develop neuroblastoma tumors." (PMID 31695841, 2019). "Prior studies have shown that treatment of neuroblastoma tumors with vandetanib, a RET, VEGFR, and EGFR inhibitor, resulted in a significant decrease in tumor angiogenesis in vivo." (PMID 31695841, 2019). "A phosphoproteomic analysis of neuroblastoma also found RET to be overexpressed and activated in neuroblastoma." (PMID 28871274, 2017). "RET is a receptor tyrosine kinase required for normal development of the nervous system that has been found to be expressed in most neuroblastomas and overexpressed in some." (PMID 26771642, 2016). "Vandetanib/ZD6474 inhibits activation of RET and was found to decrease neuroblastoma cell viability and proliferation and inhibit growth in neuroblastoma xenografts." (PMID 26771642, 2016). "Neurite outgrowth in human neuroblastoma cells stimulated by RET was shown to be regulated through downstream activation of Ras/ERK." (PMID 22355350, 2012). "Several neuroblastoma cell lines express RET together with other tyrosine kinase receptors of the GDNF family (GFR-1, -2 and -3)." (PMID 22429913, 2012). "Our results in both cell lines clearly show the crucial role of the RET proto-oncogene in retinoid-induced cell differentiation in neuroblastoma cells." (PMID 20459794, 2010). "Moreover, regorafenib was clearly established as a RET signaling inhibitor in neuroblastoma cell lines, and its tumor suppressant effect was validated in vivo in a xenograft tumor system and in the immuno-competent TH-MYCN transgenic mouse model." (PMID 34716856, 2022).
neuroblastoma (continued). "Remarkably, we could show that loss of RET results in a striking epithelial-to-mesenchymal transition (EMT) phenotype, and we provide evidence that RET activity suppresses the mesenchymal phenotype in neuroblastoma." (PMID 33921066, 2021). "To investigate whether RXDX-105 is able to inhibit the RET kinase and the RAS-MAPK pathway in neuroblastoma cells, we evaluated a panel of neuroblastoma cell lines for RET, MEK, and ERK expression and phosphorylation after 24 hours of treatment with RXDX-105." (PMID 31695841, 2019). "RET inhibition has been found to be effective in in vitro and in vivo preclinical models of neuroblastoma, and a recently opened clinical trial (NCT03611595) will evaluate the efficacy of the combination of RET inhibition and retinoid therapy in children with neuroblastoma and other solid tumors." (PMID 30384486, 2018). "The potential interaction of each of these molecules in RET signaling (except for ALK), indicates that this “pair” may be a linked activation complex in neuroblastoma." (PMID 28871274, 2017). "Interestingly, other PCDH family members were demonstrated to stabilize RET signaling in neuroblastoma, indicating that PCDHs play a role in tumor cell signaling and activation." (PMID 28871274, 2017). "Furthermore, our data provide evidence that activated ALK triggers RET upregulation in mouse sympathetic ganglia at birth as well as in murine and human neuroblastoma." (PMID 24811913, 2014). "As expected, we could detect very low levels of RET receptor on IMR-32 and SK-N-MC cells, two neuroblastoma cell lines shown to have small amount of RET transcripts." (PMID 23527089, 2013). "The role of RET gene in neuroblastoma has been debated for several years." (PMID 22429913, 2012). "It is interesting to note that no RET mutation has been observed in familial neuroblastoma although this malignancy onsets frequently in the first year of life indicating that the carcinogenesis process already starts during the embryonic life." (PMID 22429913, 2012). "Experimental evidences indicate that abnormal RET gene expression may play a role in disturbing the physiological NC development and participate to the neuroblastoma cell formation." (PMID 22429913, 2012). "Indeed, RET is an essential gene for the development of NC the same tissue from which neuroblastoma origins." (PMID 22429913, 2012). "Several RTKs, including ALK, KIT, MET, NTRK2, and RET, play a major role in neuroblastoma pathogenesis, and their activation could be responsible for adaptive resistance to trametinib and ganitumab in neuroblastoma." (PMID 39001383, 2024). "To determine whether RXDX-105 treatment was also able to inhibit RET phosphorylation as well as the RAS-MAPK pathway in mice with neuroblastoma xenograft tumors, we evaluated lysates of harvested tumors by Western blots for total and phosphorylated RET, MEK, and ERK." (PMID 31695841, 2019). "Additionally, the RET tyrosine kinase, which is primarily expressed in cells and tissues derived from the neural crest, has been shown to be required for maturation of the peripheral nervous system, and RET was further shown to be required for neuroblastoma differentiation induced by retinoic acid." (PMID 30384486, 2018). "Additionally, we also found one patient with a variant in the receptor tyrosine kinase RET, in contrast to a previous report where no RET mutations were found in primary neuroblastomas." (PMID 28423360, 2017). "Additionally, a RET-overexpressing transgenic mouse spontaneously developed neuroblastoma." (PMID 26771642, 2016). "In SH-SY5Y neuroblastoma cells this regulation seems to be mediated through the PI3K/AKT pathway, which in turn can be activated by RET." (PMID 38666930, 2024). "Using a CRISPR TMEM127-KO in the neuroblastoma cell line SH-SY5Y, we noted significantly increased levels of endogenously expressed RET protein, which appeared primarily as the higher molecular weight fully glycosylated form found at the cell surface." (PMID 38687678, 2024).
neuroblastoma (continued). "To ascertain how many of the gut developmental TFs we identified, control RET and EDNRB, we performed siRNA-mediated knockdown of each in the human neuroblastoma cell line SK-N-SH." (PMID 37948459, 2023). "Once more, the fact that some of such RTKs have previously been described as important players in neuroblastoma tumor biology (e.g., ALK, KIT, MET, and RET) again validates this approach." (PMID 34716856, 2022). "Using neuroblastoma cell lines, we show that ALK modulates RET signaling at the level of RET phosphorylation, as well as at the level of transcription." (PMID 33921066, 2021). "Treatment with RXDX-105 inhibited RET phosphorylation and phosphorylation of the MEK and ERK kinases in neuroblastoma cells and xenograft tumors, and RXDX-105 treatment induced both apoptosis and cell cycle arrest." (PMID 31695841, 2019). "In neuroblastoma, Vandetanib exerts a dual action by targeting VEGF receptors on tumor endothelial cells and RET on tumor cells as demonstrated in neuroblastoma." (PMID 30701022, 2018). "ALK, FGFR1, RET, PDGFRA, DDR2, EGFR, and IGF1R were enriched in endosomes from two or more neuroblastoma cell lines, but there were profound differences among cell lines." (PMID 25884760, 2015). "In line with previously published analyses of HOXC9 in neuroblastoma cells, we found a significant up-regulation of genes involved in neuronal differentiation pathways such as DNER, NEFL, DBH, TH, RET, MAP2 and NPY." (PMID 25406647, 2014). "Our analysis highlights the importance of RET, IGF-1R/IR and FGFR1 as RTKs in neuroblastoma and suggests a methodology that can be used to identify potential novel biological therapeutic targets." (PMID 24349301, 2013). "Moreover, high co-expression of RET and DDR2 distinguishes neuroblastoma cell lines from virtually any other cancer cell line in the CCLE." (PMID 34716856, 2022). "With the established roles of RET and RAS/MAPK signalling in neuroblastoma pathogenesis and with the efficacy of regorafenib established in these and other studies, additional preclinical and clinical testing of regorafenib in children with neuroblastoma is clearly warranted." (PMID 32457362, 2020). "Regorafenib treatment also inhibited 13-cis-retinoic acid-induced RET phosphorylation, and led to reduced expression of FGFR1 and PDGFRβ, with incomplete inhibition of FGFR1 and PDGFRβ phosphorylation also noted in tested neuroblastoma cell lines." (PMID 32457362, 2020). "Besides ASCL1, we found that the receptor tyrosine kinase gene RET was positively regulated by LMO1 and MYCN in neuroblastoma cells." (PMID 31819055, 2019). "Our results demonstrate that RXDX-105 inhibits both RET and the RAS-MAPK pathway, which likely both contribute to the observed potent in vitro and in vivo antitumor effects and suggest that RET and its downstream RAS-MAPK pathway are involved in neuroblastoma pathogenesis." (PMID 31695841, 2019). "Inhibitors of the RET kinase and the RAS-MAPK pathway have previously been shown to be effective against neuroblastoma, suggesting that combined inhibition may have increased efficacy." (PMID 31695841, 2019). "Upon addition of glial cell line-derived neurotrophic factor (GDNF), a growth factor and ligand for RET that neuroblastoma cells secrete, cell proliferation was stimulated in non-adherent neuroblastoma cells but not in adherent cells." (PMID 26771642, 2016). "Moreover, genes that have previously been established to drive neuroblastoma progression and migration, including DBH, NOTCH1, RET and WNT1, were down regulated in response to TRPM7 knockdown." (PMID 25797249, 2015). "The overexpression of RET and the inhibition of MYCN oncogenes as markers of cell differentiation and the effect of RA as an inducer of cell differentiation in neuroblastoma cell cultures have been widely described." (PMID 23650528, 2013).
neuroblastoma (continued). "To determine the functional significance of AKT2-mediated inhibition of Gli1 transcriptional activity in neuroblastoma, we quantified the mRNA levels of RET and MATN2 as downstream targets of Gli1 with or without AKT2 overexpression." (PMID 23900341, 2013). "Notably, Gli1 did not induce N-MYC expression in neuroblastoma cells, but strongly induced RET, a known mediator of RA effect." (PMID 19834598, 2009). "Regorafenib is a multi-kinase inhibitor that targets VEGFRs, PDGFR, RET, RAF kinases, and other signaling molecules, suggesting that its impact on neuroblastoma cells may not be solely due to DHODH inhibition." (PMID 40513779, 2025).